GSTA4 (glutathione S-transferase alpha 4)
Diseases named in the same sentence as GSTA4 in open-access papers (continued):
Sharing a sentence is not in itself a finding about the gene and the disease.
prostate carcinoma (2 papers, 2012 to 2013). A carcinoma that arises from epithelial cells of the prostate gland. "The higher expression level of GSTA4 in DU145 prostate cancer cells is associated with faster 4-HNE metabolism rate, compared to PC3 or LNCaP prostate cancer cells." (PMID 23190551, 2012). "The inhibition of NRF2 expression resulted in a reduction of GSTA4 expression and GSH-4HNE formation and increased sensitivity to 4HNE-mediated antiproliferation and apoptosis in prostate cancer cells." (PMID 23766854, 2013).
adenoma (1 paper, 2023). A neoplasm arising from the epithelium. "This is consistent with previous results showing that GSTA4 specifically expressed in adenomas and carcinomas, not in normal and hyperplastic colons." (PMID 37810110, 2023).
aneurysm (1 paper, 2025). Bulging or ballooning in an area of an artery secondary to arterial wall weakening. "Hypomethylation of several genes, including CXCR4, OSM, GSTA4, MAP3K10, ADAMTS, PTBP1, and PNPLA6,61, –63,65,67,71 has been identified as being associated with the aneurysm formation." (PMID 41342741, 2025).
brain injury (1 paper, 2017). Acute and chronic (see also brain INJURIES, CHRONIC) injuries to the brain, including the cerebral hemispheres, CEREBELLUM, and brain STEM. "A later study determined Glutathione S-transferase alpha 4 (Gsta4) as the strongest candidate gene regulating neurodegeneration in response to VRA and traumatic brain injury (TBI) in DA.VRA1 congenic rats." (PMID 28672859, 2017).
cervical cancer (1 paper, 2022). A primary or metastatic malignant neoplasm involving the cervix. "In a variety of tumors, such as drug‐resistant cervical cancer, the expression of GSTA4 is increased, suggesting that GSTA4 is related to tumor survival and drug resistance." (PMID 35048517, 2022).
cholestasis (1 paper, 2017). Impairment of the bile flow caused by obstruction within the liver, or outside the liver in the bile duct system. "After ANIT-induced cholestasis was treated with fenofibrate, the levels of Gsta2, Gsta4, Gstm3, and Gpx2 were significantly decreased (P < 0.01)." (PMID 28855630, 2017). "In our study, the expression levels of Gsta2, Gsta4, Gstm3 and Gpx2 were increased in the ANIT-induced cholestasis." (PMID 28855630, 2017).
colon adenocarcinoma (1 paper, 2025). "To investigate the association of GSTA4 with macrophage ferroptosis in human CRC, we analyzed macrophage-specific expression of GSTA4 and GPX4 along with macrophage proportions in human colon adenocarcinomas (COAD) and rectal adenocarcinomas (READ) using TCGA database." (PMID 39819335, 2025).
colon adenoma (1 paper, 2023). An adenoma that arises from the colon. "It has been reported that knock-down of glutathione S-transferase alpha 4, which is a 4-HNE detoxifying enzyme, in Min mice increased the multiplicity of colon adenoma and decreased the survival rate." (PMID 38072949, 2023).
colorectal adenoma (1 paper, 2023). An adenoma that arises from the colon or rectum. "Previous studies have shown that GSTA4 and 4-HNE adducts are highly expressed in human colorectal adenomas and carcinomas as well as in murine CRC models." (PMID 37810110, 2023).
demyelination (1 paper, 2020). "The Gsta4 effect on apoptosis during adult OL differentiation was corroborated in vivo in both lysolecithin-induced demyelination and experimental autoimmune encephalomyelitis models, where Casp8 activity was reduced in Gsta4-overexpressing OLs." (PMID 32792491, 2020).
epilepsy (1 paper, 2016). A brain disorder characterized by episodes of abnormally increased neuronal discharge resulting in transient episodes of sensory or motor neurological dysfunction, or psychic dysfunction. "However, variation at GSTA4 has been associated with epilepsy remission following pharmacological intervention, suggesting a possible role in drug metabolism in addition to a putative neuroprotective role." (PMID 26829228, 2016).
experimental autoimmune encephalomyelitis (1 paper, 2020). An autoimmune demyelinating disease of the central nervous system that is produced experimentally in animals by the injection of homogenized brain or spinal cord in Freund's adjuvant. "To address the implications of Gsta4 over-expression in a model of autoimmune demyelination we induced experimental autoimmune encephalomyelitis (EAE) in DAWt and DAGsta4 rats by sub-cutaneous injection of recombinant myelin oligodendrocyte glycoprotein (MOG) in adjuvant." (PMID 32792491, 2020).
injury (1 paper, 2025). Damage inflicted on the body as the direct or indirect result of an external force, with or without disruption of structural continuity. "A natural variation in Gsta4 expression in rats that affects degeneration after a traumatic brain injury has also been described but is not narrated concerning a peripheral nerve injury." (PMID 40356597, 2025).
intracranial aneurysm (1 paper, 2022). "The receiver operating characteristic (ROC) curve showed that GSTA4 mean methylation (AUC = .80, p < .001) was a reliable predictor of women intracranial aneurysm, among which CpG 1 exhibited the best predictive value (AUC = .89, p < .001)." (PMID 36699470, 2022).
ischemia (1 paper, 2012). A hypoperfusion of the BLOOD through an organ or tissue caused by a PATHOLOGIC CONSTRICTION or obstruction of its BLOOD VESSELS, or an absence of BLOOD CIRCULATION. "The expression of Hmox1, Gclc and Gsta4, all phase II enzymes with Nrf2 related expression, was determined 12 hours after treatment with vehicle, photothrombotic ischemia alone or photothrombotic ischemia and low dose (5 mg/kg) sulforaphane." (PMID 22911746, 2012).
migraine (1 paper, 2022). "The causal effect of lower levels of GSTA4, an antioxidant enzyme, on migraine is consistent with previously reported higher levels of oxidants (such as nitric oxide) and lower levels of antioxidants (such as glutathione and glutathione S-transferase) in migraine patients." (PMID 35546551, 2022). "Hence, our findings suggest that the imbalance between production and detoxification of oxygen reactive species in migraine patients might be caused by lower levels of GSTA4." (PMID 35546551, 2022). "Lastly, our scan for inferring causality identified five blood proteins (DKK1, PDGFB, GSTA4, FARS2 and CHIC2) with a significant genetic causality on migraine." (PMID 35546551, 2022). "We show that higher levels of DKK1 and PDGFB, and lower levels of FARS2, GSTA4 and CHIC2 proteins have a significant causal effect on migraine." (PMID 35546551, 2022). "Additionally, our LCV analyses found a significant genetic causality on migraine for lower levels of three blood proteins, including FARS2, GSTA4 and CHIC2." (PMID 35546551, 2022). "In addition, we identified that higher levels of DKK1 and PDGFB, and lower levels of FARS2, GSTA4 and CHIC2 causally increase the risk of migraine." (PMID 35546551, 2022).
pancreatic cancer (1 paper, 2025). "The immunohistochemistry experiment once again confirmed that GSTA4 exhibits an abnormally low expression characteristic in pancreatic cancer." (PMID 40375987, 2025).
periodontitis (1 paper, 2025). An acute or chronic inflammatory process that affects the tissues that surround and support the teeth. "On the other hand, we found that peroxidase (GPX2) and glutathione S-transferase (GSTA4) are upregulated in the gingival tissue of periodontitis patients." (PMID 41333919, 2025). "The biological functions and mechanistic roles of the predicted genes—such as GPX2, CD34, and GSTA4—in the pathogenesis of periodontitis remain to be empirically confirmed." (PMID 41333919, 2025). "These genes have been previously implicated in oxidative stress (GPX2 and GSTA4), immune regulation (CD34 and IGKV2D-30), and RNA processing (NYNRIN), which are all biologically relevant to the inflammatory and immune mechanisms underlying periodontitis." (PMID 41333919, 2025). "Similarly, GSTA4 (5 SNPs, OR = –0.205, 95% CI: –0.391 to –0.020, p=0.031), NYNRIN (5 SNPs, OR = –0.174, 95% CI: –0.298 to –0.050, p=0.006), and IGKV2D-30 (3 SNPs, OR = –0.405, 95% CI: –0.809 to –0.002, p=0.049) were all inversely associated with periodontitis, implying potential protective roles." (PMID 41333919, 2025). "The corresponding results revealed that, compared to control samples, IGKV2D-30 and CD34 were downregulated in patients with periodontitis, while GPX2, GSTA4, and NYNRIN were upregulated in patients with periodontitis." (PMID 41333919, 2025).
peritoneal effusions (1 paper, 2005). "Pleural effusions had significantly higher expression of the angiogenic inducer CYR61, RAB21, glutathione S-transferase A4 (GSTA4), and several chemokines when compared to peritoneal effusions." (PMID 16042759, 2005).
sarcopenia (1 paper, 2020). Progressive decline in muscle mass due to aging which results in decreased functional capacity of muscles. "Further analysis of pathways activated by Gpx1 and Gsta4 warrant attention because dissection of the involved mechanisms could lead to new therapies for sarcopenia." (PMID 33067900, 2020). "Increased capacity for enzymatic scavenging of superoxide radical could be a major protective adaptation against free radical damage in muscle and may therefore be a major protection against the development or onset of sarcopenia, and Gpx1 and Gsta4 might additionally be involved." (PMID 33067900, 2020).
steatosis (1 paper, 2012). Increased lipid within the cytoplasm of cells. "The gene GSTA4, which is found to be up-regulated in the fibroblasts of the two steatosis patients, catalyzes the reaction of reduced glutathione to 4-hydroxynonenal, a product which is considered as a marker for oxidative damage in tissue." (PMID 22969728, 2012). "In contrast to GSTM2, GSTM1, GSTA4, and GPX4 which are up-regulated in the steatosis patients, GSTT1 is found to be down-regulated." (PMID 22969728, 2012).
Stroke (1 paper, 2012). Sudden impairment of blood flow to a part of the brain due to occlusion or rupture of an artery to the brain. "Gsta4 only significantly increased in stroke combined with sulforaphane treatment compared to vehicle (p≤0.05)." (PMID 22911746, 2012).
systemic lupus erythematosus (1 paper, 2025). An autoimmune multi-organ disease typically associated with vasculopathy and autoantibody production. "Similarly, the low expression of GSTA4 was enriched in pathways, like chemokine signaling pathway, cytokine–cytokine receptor interaction, hematopoietic cell lineage, oxidative phosphorylation, systemic lupus erythematosus, among others." (PMID 41333919, 2025).
ulcerative colitis (1 paper, 2023). An inflammatory bowel disease involving the mucosal surface of the large intestine and rectum. "GSTA4, as an antioxidative biomarker, is strongly expressed in the colon biopsies from ulcerative colitis patients compared to healthy controls." (PMID 37810110, 2023).
cancer (16 papers, 2018 to 2025). A tumor composed of atypical neoplastic, often pleomorphic cells that invade other tissues. "Further research is warranted to fully elucidate the potential cancer preventive effect of Gsta4 deficiency through the use of organoid, patient-derived xenograft, and other CRC models." (PMID 39819335, 2025). "We tested the logical prediction of this observation by examining the cancer susceptibility of GSTA4 knockout mice that have higher baseline levels of 4-HNE but found no reduction in their sensitivity to chemical carcinogenesis." (PMID 34944997, 2021). "Additionally, inactivation of GSTA4 increases intracellular ROS and cancer cell susceptibility to the chemotherapeutic agents, 5-FU and oxaliplatin." (PMID 35936694, 2022). "GSTK1-1 is the main GST isoform in the mitochondrial matrix, but the GSTA1-1 and GSTA4-4 isoforms are also thought to be in the mitochondria with their distribution altering in transformed cells, thus potentially providing a cancer specific target." (PMID 38593670, 2024). "The upregulation of GSTA4 to counteract oxidative stress underscores the adaptability of cancer cells, highlighting the complex interplay between tumors and the host immune system." (PMID 38791327, 2024). "This dual benefit to the cancer cells positions GSTA4 as a potential marker for therapeutic targeting." (PMID 38791327, 2024). "Overexpression of GSTA4 and GSTP1 is associated with the development of cisplatin resistance in human cancer cells of erythroleukemia, mammary, and ovary adenocarcinomas." (PMID 35936694, 2022). "(iv) Glutathione S-transferase alpha 4 (GSTA4), which is one of the 16 human cytosolic GSTs, is downregulated only in cancer cell lines." (PMID 32365991, 2020). "Many GSTs, e.g., GSTO1, GSTP1, GSTK1, GSTA4 and GSTM3, are reported to cause resistance in cancer." (PMID 36428646, 2022). "GSTA4 is abnormally expressed in and affects the progression of a variety of malignant tumors." (PMID 35048517, 2022). "Genetic associations have been made between GSTA4 mutations and risk for certain types of cancer, but not much is known about the role of GSTA4 in PD." (PMID 29681884, 2018). "However, the impact of GSTA4 in submucosal cells, particularly in macrophages during inflammation and cancer initiation remains unclear." (PMID 39819335, 2025). "The expressions of NRF2 target gene Nqo1 and Gsta4 were also downregulated in the DKO 3LL cell line, demonstrating successful reversal of NRF2 hyperactivation in the KEAP1-KO cancer cells." (PMID 41035689, 2025). "To finesse this approach to target particular GST isoforms in the context of cancer, here we have determined the kcat/Km for the human isoforms of GSTK1-1, GSTA1-1 and GSTA4-4 with respect to GSH and CDNB." (PMID 38593670, 2024). "GSTA4 can protect cells from oxidative stress products and can detoxify 4‐HNE in normal cells and many cancer cells by catalyzing the formation of an adduct of GSH and 4‐HNE." (PMID 35048517, 2022). "Inhibitors of 4-HNE-metabolizing enzymes including GSTA4, AKR, ALDH or Rlip are selectively toxic to cancer cells." (PMID 34944997, 2021). "Genes such are GSTA4, GSTO2, KLK3, PGF were down-regulated and E2F2, MMP9, PIM2, VEGFC are up-regulated in all cancer nodules." (PMID 34209090, 2021). "Further insight into the cancer-related gene expression unraveled that 22 of DEGs were upregulated by shNrf1, of which 4 genes (i.e., RAC3, PDGFA, GSTA4, and RXRA) were downregulated by Nrf1α−/− (, and )." (PMID 32273945, 2020). "According to both the Gene Expression Omnibus and The Cancer Genome Atlas, only GSTA4 mRNA levels were higher in tumor tissues than non-tumor tissues." (PMID 29507666, 2018).
tumor (12 papers, 2014 to 2026). "Gsta4 loss induces ferroptosis and blocks pro-tumor signaling." (PMID 40919170, 2025). "Finally, we investigated the effect of GSTA4-deficiency on tumorigenesis using a xenograft tumor model." (PMID 35936694, 2022). "Finally, inactivation of GSTA4 inhibited xenograft tumor growth and increased susceptibility to 5-FU and oxaliplatin in vivo." (PMID 35936694, 2022). "The observations that C57BL/6.Psl1BH1dba mice were more sensitive than C57BL/6 mice and that C57BL/6.Psl1H6dba mice had a tumor response similar to C57BL/6 are consistent with the conclusion that Gsta4 is a tumor promotion susceptibility gene as recently reported." (PMID 24700353, 2014). "The pseudotime analysis indicates that GSTA4 exhibits high expression levels in the intermediate state of tumor cells." (PMID 41982811, 2026). "As a prognostic protective factor, GSTA4 exhibits downregulated expression in PC tissues and suppresses tumor proliferation and migration, highlighting its potential as a therapeutic target." (PMID 40375987, 2025). "Analysis of the GSE28735, GSE62452, and GSE71729 datasets revealed significantly lower GSTA4 expression in PC tumor tissues compared to normal pancreatic tissues." (PMID 40375987, 2025). "This study elucidates the impact of GSH metabolism-related genes on the PC tumor microenvironment at the single-cell level and identifies GSTA4 as a critical prognostic molecular marker." (PMID 40375987, 2025). "Surprisingly, we also found high expression levels of lipid metabolism genes in the B16F10 tumor cell subpopulation, including Gsta4, Gsta2, Gstp1, and Enpp2." (PMID 38755254, 2024). "The results showed that the expression level of GSTA4 in tumor tissue was significantly higher than that in normal brain tissue." (PMID 35048517, 2022). "Curzerene‐treated tumor tissues showed decreased GSTA4 levels and decreased proliferation, invasion, and migration, accompanied by increased apoptosis, decreased GST catalytic activity, and increased 4‐HNE." (PMID 35048517, 2022). "Gsta4 prevents macrophage ferroptosis and maintains pro-tumor bystander effects." (PMID 40919170, 2025). "Despite the comprehensive analysis of the intricate roles of GSH metabolism-related genes in the tumor microenvironment using single-cell and transcriptome data from PC, and the successful in vitro validation of the key target GSTA4, the study has inherent limitations." (PMID 40375987, 2025). "Targeting Gsta4 can inhibit microbiota-driven tumor progression." (PMID 40919170, 2025). "For saline-treated mice, the average tumor size significantly decreased for HCT116ΔGSTA4-derived xenografts compared with HCT116-derived xenografts (P <0.001), indicating reduced tumor growth for GSTA4-deficient HCT116 cells." (PMID 35936694, 2022). "GSTA4 is up-regulated in tumor cells during drug resistance to cisplatin and doxorubicin." (PMID 26745821, 2016). "Likewise, disruption of glutathione S-transferase alpha 4 (GSTA4) enhances ferroptotic sensitivity in macrophages and prevents microbiota-driven colorectal tumorigenesis, highlighting ferroptosis as both a cytotoxic pathway and a regulator of immune–tumor interactions." (PMID 41228309, 2025). "As 4-HNE initiates CRC via mediating microbiota-induced bystander effect and Gsta4 promotes CRC cell proliferation, the results from the current study further support the tumor-promoting roles of 4-HNE and Gsta4." (PMID 37810110, 2023). "Our results show that inactivation of GSTA4 in HCT116 cells reduces cell proliferation and increases chemotherapeutic drug sensitivity in vitro and in a xenograft tumor model." (PMID 35936694, 2022).
bacterial infections (3 papers, 2016 to 2025). "Interestingly, a negative correlation could be established between the GSTA4 expression level and the development of bacterial infections both in human and mice." (PMID 29535973, 2018).
infection (2 papers, 2016 to 2019). The state of being infected such as from the introduction of a foreign agent such as serum, vaccine, antigenic substance or organism. "The expression of mRNAs for Cadherin, Albumin, GstA4 and AFP were significantly increased 20 and 40 days after the first infection and those for MaoA and MaoB were augmented to some extent." (PMID 28352551, 2016).
adenocarcinoma (1 paper, 2009). A common cancer characterized by the presence of malignant glandular cells. "RT-PCR confirmed that amphiregulin (Areg), epiregulin (Ereg), fetuin beta (Fetub), claudin 2 (Cldn2), hepatic nuclear factor 4, alpha (Hnf4α), glutathione S-transferase, alpha 4 (Gsta4) and forkhead box A3 (Foxa3) were up-regulated in adenocarcinoma." (PMID 19812696, 2009).